KLF4 (KLF transcription factor 4)
Diseases named in the same sentence as KLF4 in open-access papers (continued):
Sharing a sentence is not in itself a finding about the gene and the disease.
pancreatic cancer (59 papers, 2009 to 2026). "It has been shown that overexpression of DNMT1 leads to KLF4 promoter hypermethylation, which contributes to decreased expression and is associated with poor differentiation of pancreatic cancer." (PMID 37239940, 2023). "KLF4 is implicated in tumor progression of pancreatic cancer, but the molecular regulatory mechanism of KLF4 needs to be further specified." (PMID 35027543, 2022). "In the pancreatic cancer cell lines, the Klf4 expression is associated with increased doubling time i.e. slower growth." (PMID 20514221, 2009). "AS of KLF4 pre-mRNA has been reported in pancreatic cancer, generating five different intron-skipping isoforms." (PMID 40552304, 2025). "Western blotting can assess expression changes of the corresponding protein target after miRNA modulation, as with miR-27b regulation of Krüppel-like factor 4 (KLF4) in pancreatic cancer." (PMID 41347080, 2025). "In pancreatic cancer, increased expression of DNMT1 and aberrant methylation of promoters implicated in the downregulation of KLF4 expression result in impaired differentiation and unfavourable outcomes." (PMID 40387409, 2025). "UFMylation of ribosomal protein L10 (RPL10)in pancreatic cancer tissues enhances cell proliferation and promotes cancer cell stemness by upregulating Krüppel-like factor 4 (KLF4) expression." (PMID 41179291, 2025). "KLF4 inhibits tumor growth in the advanced stage of pancreatic cancer, while it plays the opposite role in the precancerous lesions." (PMID 37031197, 2023). "KLF4 expression is significantly decreased in pancreatic cancer and correlates with the invasion and pancreatic disease stage." (PMID 37239940, 2023). "The so-far-discovered driving forces for metastases in pancreatic cancer are numerous non-coding RNAs, transcription factors (like Kruppel-like factor 4, KLF4), growth factors (like vascular endothelial growth factor, VEGF), and oxygen conditions." (PMID 37685710, 2023). "KLF4 plays an important role in the development and progression of various types of cancers, including lung, breast, colorectal and pancreatic cancers." (PMID 37031197, 2023). "Conversely, in pancreatic cancer, KLF4 executes an alternative role and inhibits tumor progression by transcriptionally repressing the lactate dehydrogenase (LDHA) enzyme." (PMID 37835497, 2023). "We aimed to probe molecular regulatory mechanism of KLF4 in malignant progression of pancreatic cancer." (PMID 35027543, 2022). "In summary, we validated the impact of miR-135b-5p/KLF4/GPRC5A regulatory axis on pancreatic cancer cells." (PMID 35027543, 2022). "To inquiry about the molecular mechanism of KLF4 expression in pancreatic cancer progression, we explored the downstream genes of KLF4." (PMID 35027543, 2022). "This study unveiled molecular mechanism of miR-135b-5p/KLF4/GPRC5A axis in human pancreatic cancer cells and demonstrated the probability of miR-135b-5p as a new therapeutic target." (PMID 35027543, 2022). "Above all, this research attempted to clarify molecular mechanism whereby miR-135b-5p regulates KLF4/GPRC5A to affect malignant progression of pancreatic cancer cells." (PMID 35027543, 2022). "We explored the key gene, which was regulated by KLF4 and differentially expressed to understand the regulatory mechanism of KLF4 in pancreatic cancer." (PMID 35027543, 2022). "Then, KLF4 level in pancreatic cancer cells was assayed through qRT-PCR, and it was disclosed that relative to normal cells, KLF4 mRNA level was markedly decreased in cancer cell lines." (PMID 35027543, 2022). "Recent research indicates that KLF4 expression in pancreatic cancer tissue and cells is relatively low to normal pancreatic tissue and cells." (PMID 35027543, 2022). "But a study offers contradictory findings that KLF4 is upregulated in invasive pancreatic cancer cells and human tumor tissues, and facilitates tumor growth in mice." (PMID 35027543, 2022).
pancreatic cancer (continued). "For example, phosphorylated STAT3 can upregulate KLF4 level to maintain stemness of pancreatic cancer cells." (PMID 35027543, 2022). "MiR-135b-5p fostered malignant behaviors of pancreatic cancer cells by decreasing KLF4, while KLF4 hampered the disease by negatively modulating the transcriptional expression of GPRC5A." (PMID 35027543, 2022). "Earlier clinical evidence existed that KLF4 is lowly expressed in pancreatic cancer tissues, particularly in the advanced stage, which is congruous with our results." (PMID 35027543, 2022). "As such, our results indicated that GPRC5A was upregulated in pancreatic cancer, and upregulated expression of KLF4 also inhibited the expression of GPRC5A." (PMID 35027543, 2022). "In conclusion, this study provided significant insights into the miR-135b-5p/KLF4/GPRC5A axis in pancreatic cancer progression." (PMID 35027543, 2022). "Supporting these in vitro observations, in pancreatic cancer samples, KLF4 correlated positively with E-cadherin and negatively with vimentin and Cav-1, a direct transcriptional target of KLF4 that can inhibit EMT in pancreatic cancer." (PMID 34680284, 2021). "Klf4, which is a tumor suppressor for pancreatic cancer, is positively correlated with E-cadherin expression." (PMID 33110361, 2020). "Depending on tumor type, KLF4 is thought to be a tumor suppressor in gastrointestinal, esophageal, lung, and pancreatic cancers, while it acts as an oncogenic player in breast and squamous cell carcinoma." (PMID 33231937, 2020). "Recently, KLF4 was reported to transcriptionally repress cavelion-1 expression and thereby inhibit metastasis of pancreatic cancer." (PMID 30658712, 2019). "KLF4α is one of the main isoforms of KLF4 and was found to be over-expressed in pancreatic cancer and to correlate with poor patient prognosis." (PMID 30555344, 2018). "Genetic ablation of KLF4 in pancreatic cancer cells isolated from KLF4 flox/flox mice significantly increase CD44 expression." (PMID 29747682, 2018). "One of the main KLF4 isoforms, KLF4α, has been shown to be over-expressed in pancreatic cancers and to correlate with the aggressiveness of tumors and poor patient prognosis." (PMID 27323810, 2016). "KLF4 was originally identified as a tumor suppressor in several cancers including gastrointestinal, esophageal, lung and pancreatic cancers." (PMID 27105535, 2016). "A novel Krüppel-like factor 4 (KLF4) regulates aerobic glycolysis in pancreatic cancer through negatively regulating the transcription of LDHA." (PMID 26918353, 2016). "Ectopic expression of Klf4 in pancreatic cancer lines also leads to cell cycle arrest and marked growth inhibition in vitro." (PMID 20514221, 2009). "Similarly, in pancreatic cancer, KLF4 also exhibits a relatively consistent tumor‐suppressing effect." (PMID 41532367, 2026). "Consequently, this upregulation hinders the expression of DNMT1 protein and its interaction with the promoter region of KLF4, resulting in a decrease in promoter DNA methylation and the activation of KLF4 expression within pancreatic cancer cells." (PMID 40387409, 2025). "Also, modulation of KLF4 expression substantially impacts the expressions of differentiation markers in cells afflicted with pancreatic cancer." (PMID 40387409, 2025). "Thus, upregulation of KLF4 in PDAC positively impacts pancreatic cancer progression by promoting glycolysis and facilitating angiogenesis and EMT." (PMID 37239940, 2023). "In the same study, the authors showed that DIM significantly induced miR-152 expression, blocking DNMT1, its binding to KLF4 promoter, thus, activating KLF4 expression, and inhibiting cell growth in vitro and tumorigenesis in animal models of pancreatic cancer." (PMID 37239940, 2023). "Another study supported KLF4’s self-renewal role in pancreatic cancer stem cells." (PMID 37239940, 2023).
pancreatic cancer (continued). "This review summarizes the major functions and regulatory mechanisms of KLF4 in ten common cancers in an attempt to discover its unique tumor regulatory role, and propose KLF4 as a potential therapeutic target and clinical biomarker in tumors, especially pancreatic cancer (PDA)." (PMID 37031197, 2023). "Next, to find out the underlying player(s) related to the change of cell stemness, we chose four major transcription factors that are commonly related to the stemness of pancreatic cancer cells, including KLF4, SOX2, Nanog and Oct4, to identify potential molecules for the regulation of the stemness." (PMID 37280198, 2023). "KLF4 plays an essential role in the initiation of pancreatic cancer development." (PMID 37239940, 2023). "Wei and colleagues showed that KLF4 could exist in four isoforms in pancreatic cancer because of cis-splicing." (PMID 37239940, 2023). "Also, there is increasing evidence that KLF4 can promote the precancerous lesions, such as the early lesions of pancreatic cancer, ADM and PanIN." (PMID 37031197, 2023). "Both in vivo and in vitro experiments verified that miR-135b-5p could affect malignant progression of pancreatic cancer through KLF4/GPRC5A." (PMID 35027543, 2022). "Meanwhile, to assay whether miR-135b-5p could affect pancreatic cancer cell function by regulating KLF4, we set up 3 cell groups and conducted a series of cell function experiments for verification." (PMID 35027543, 2022). "In conclusion, our experimental data demonstrated that low miR-135b-5p level could affect GPRC5A by KLF4, thus hindering cell malignant phenotypes of pancreatic cancer, but the inhibitory effect could be reversed by overexpressing GPRC5A." (PMID 35027543, 2022). "The reasons may be that KLF4 is not only regulated by miR-135b-5p in pancreatic cancer cells, but also be regulated by other genes and cytokines." (PMID 35027543, 2022). "Besides, in vivo and in vitro upregulating KLF4 are reported to hinder growth and metastasis of pancreatic cancer cells, while knocking down KLF4 exerting the opposite effect." (PMID 35027543, 2022). "In conclusion, miR-135b-5p could hamper KLF4, thus promoting proliferation, migration, and invasion, as well as hindering apoptosis of pancreatic cancer cells." (PMID 35027543, 2022). "KLF4 was discovered to be downregulated in GC and pancreatic tumor." (PMID 35768405, 2022). "We detected the expression of several markers of cell stemness, such as CD44, CD133, OCT4, Nanog, and KLF4, to test whether the effect of Arl4c on promoting drug resistance in pancreatic cancer is attributed to its role in regulating cell stemness." (PMID 34849465, 2021). "Furthermore, DNMT1 inhibition reduces KLF4 promoter DNA methylation and activates KLF4 expression in pancreatic cancer cells." (PMID 33596966, 2021). "Despite the knowledge about its role in gastrointestinal and pancreatic cancers, the process through which abnormal accumulation of KLF4 that promotes malignant transformation in mammary glands and skin remains unclear." (PMID 33231937, 2020). "Specifically, KLF4 was recently classified as a critical initiator of early pancreatic cancer." (PMID 33052880, 2020). "Interestingly, the same proximal region of CDKN1B promoter was recently shown to contain three cis elements for KLF4 transcription factor close to the AP-2 sites and to be induded by KLF4 in pancreatic cancer cell lines." (PMID 19672266, 2009). "Therefore, we concluded that stemness could be positively modulated by LOXL2 in gemcitabine-resistant pancreatic cancer cells with the exception of KLF4 expression." (PMID 37737908, 2023). "Therefore, we believe that GPRC5A may be affected by KLF4 in pancreatic cancer and thus take an essential regulatory part." (PMID 35027543, 2022). "Therefore, we believe that KLF4 may take a regulatory part in pancreatic cancer as the downstream target of miR-135b-5p." (PMID 35027543, 2022). "Therefore, miR-135b-5p decreased KLF4 in pancreatic cancer cells." (PMID 35027543, 2022).
pancreatic cancer (continued). "Therefore, we tried to excavate the genes which are regulated by KLF4 in pancreatic cancer, finding that the promoter region of GPRC5A could be regulated by KLF4." (PMID 35027543, 2022). "This disclosed that miR-135b-5p could modulate GPRC5A in pancreatic cancer cells by targeting KLF4." (PMID 35027543, 2022). "In conclusion, our findings establish PRRG1 as a key driver of pancreatic cancer progression through PI3K/Akt pathway activation and KLF4-mediated transcriptional regulation." (PMID 42108282, 2026). "Klf4 binds to the promoter region of LDHA, thus regulating LDHA expression in pancreatic cancer cells." (PMID 40593465, 2025). "Recent studies also find that FOXM1 upregulates LDHA transcription to enhance lactate production and promote cancer growth and metastasis, whereas KLF4 negatively regulates LDHA gene expression and is involved in the progression of pancreatic cancer." (PMID 39930542, 2025). "In this manner, induction of the miR‐152/DNMT1/KLF4 signalling pathway through epigenetic mechanisms by dietary DIM leads to the differentiation and substantial growth suppression of pancreatic cancer cells." (PMID 40387409, 2025). "Recently, several studies have shown that the transcriptional and post-translational regulation of LDHA by KLF4, FOXM1 and lysine-5 acetylation promotes aerobic glycolysis and the progression of pancreatic cancer." (PMID 39930542, 2025). "To further explore the relationship between KLFs and the prognosis of patients with pancreatic cancer, univariate Cox regression was performed, and we identified 4 significantly prognostic genes (KLF3, KLF4, KLF5, KLF6) with p < 0.05." (PMID 38773440, 2024). "CSCs obtained from primary patient-derived pancreatic cancer cells showed a positive correlation between higher telomerase activity and longer telomeres and stemness factors (NANOG, OCT3/4, SOX2, KLF4)." (PMID 37239940, 2023). "Contrary to the studies above, Yan and colleagues show that KLF4 and CD44 expression is mutually exclusive, specifically within human metastatic pancreatic tumors and in autochthonous mouse models of PDAC." (PMID 37239940, 2023). "For example, in recent studies, circulating tumor cells (CTC)-iChip technology is applied to purify CTC from pancreatic cancer patients for RNA-seq characterization, displaying the enrichment of main relevant genes in the stem genes LIN28B/KLF4." (PMID 35027543, 2022). "Direct binding of KLF4 to the promoter region of caveolin-1 and reduced the level of caveolin-1 to inhibit EMT and metastasis in pancreatic cancer." (PMID 35768405, 2022). "miR-135b-5p is an oncogene that negatively regulates KLF4 expression by direct binding to its 3′UTR region, resulting in reduced levels of KLF4 and activation of G protein-coupled receptor class C group 5-member A (GPRC5A), and promoting the malignant progression of pancreatic cancer." (PMID 37239940, 2023). "Unlike TES, LDHA together with KLF4 or c-Myc has been found to positively regulate aerobic glycolysis and promote tumor progression in pancreatic cancer." (PMID 35789607, 2022). "Our results stressed that KLF4, as a vital target of miR-135b-5p, could influence promoter region of GPRC5A, thus affecting the malignant progression of pancreatic cancer." (PMID 35027543, 2022). "In summary, we fully elucidated the negative modulatory relationship of miR-135b-5p and KLF4, as well as regulatory mechanism linking this relationship to pancreatic cancer cells." (PMID 35027543, 2022). "KLF4 as a tumor repressor negatively modulates CD44 and restrains metastasis of pancreatic cancer." (PMID 35027543, 2022). "HTFtarget database was employed for prediction of downstream regulatory genes of KLF4, and notably upregulated 35 genes in microarray GSE22780 were then intersected with the predicted genes, and the most obvious difference in pancreatic cancer was found in the expression of GPRC5A." (PMID 35027543, 2022).
pancreatic cancer (continued). "Furthermore, CD44V3 knockdown significantly suppressed the expression of multiple stemness markers, including BMI1, KLF4, SOX2, and NANOG, indicating that, in accordance with CD44V, CD44V3 possesses stemness-maintaining ability and then promotes pancreatic cancer migration and invasion." (PMID 36292918, 2022). "Our research unveiled that miR-135b-5p was markedly dysregulated in pancreatic cancer, and it could regulate transcription factor KLF4, but the specific molecular mechanism has not been clarified." (PMID 35027543, 2022). "From these findings we conclude that the expression level of Klf4 by itself may not be sufficient to exert a robust effect, rather, Nanog might play a more potentiating role in sphere formation in metastatic pancreatic cancer." (PMID 33110361, 2020). "However, there is a negative correlation between KLF4 and LDHA expression in pancreatic cancer cells, and KLF4 binds directly to the promoter regions of the LDHA gene and negatively regulates its transcription activity." (PMID 26062441, 2015). "Alternatively but not mutually exclusively, different KLF4 isoforms may exist to deliver different functions as recently reported in pancreatic cancer cells." (PMID 22745808, 2012). "Since KLF4 plays an important role in maintaining the stemness and self-renewal propensity of pancreatic cancer cells and promoting the progression of PAAD, it could be a key transcription factor in the regulation of ufmylation for the stemness of pancreatic cancer cells." (PMID 37280198, 2023).